TNF (tumor necrosis factor)
Diseases named in the same sentence as TNF in open-access papers (continued):
Sharing a sentence is not in itself a finding about the gene and the disease.
neutropenia (continued). "• Administration of imatinib or nilotinib before instillation of LPS during neutropenia recovery significantly downregulated several inflammatory and chemotactic cytokines, such as TNF-α, IL-6 and IL-1ß." (PMID 23787115, 2013). "In addition to the elevated levels of TNFα and IL-6, we also observed that IL-10 was enhanced by neutropenia during LPS-induced inflammation at both time points investigated." (PMID 40534875, 2025). "Multiple immunological mechanisms have been proposed to elucidate the destruction of red blood cell precursors in RPCA, and one such mechanism similar to LGL neutropenia is the overproduction of TNF- α and IFN-γ, which can lead to the apoptosis of erythroid precursors in the BM, resulting in PRCA." (PMID 38610985, 2024). "In LGLs, the overproduction of TNF-α and IFN-γ can lead to the activation of the Fas-L pathway and stimulate the production of reactive oxygen species (ROS), which can cause direct damage to the BM microenvironment, worsening neutropenia." (PMID 38610985, 2024). "However, one hypothetic mechanism for anti-TNF-α therapy-induced neutropenia relies on the impact of drugs that serve as haptens and sensitize neutrophils or neutrophil precursors, resulting in immune-mediated peripheral destruction." (PMID 31480527, 2019). "In the discovery cohort, 18 genetic variations in genes encoding four NRs (HNF4α, PXR, PPARs, and VDR), one transcription factor (NF-κB), and one cytokine (TNF) emerged as significant (p < 0.05) predictors of severe neutropenia over the entire course of chemotherapy." (PMID 29706892, 2018). "Finally, instead of increasing the circulating number of neutrophils, the option to medically treat neutropenia by inflammatory cytokines, such as interferon γ and tumor necrosis factor α, yields a modulation of the immune response by the stimulation and activation of neutrophils in blood." (PMID 29670632, 2018). "We found that the concentrations of TNF-α, IL-6, IL-1ß, and MPO were dramatically increased in BAL fluid after LPS administration during neutropenia recovery." (PMID 23787115, 2013). "The concentrations of tumor necrosis factor-α, interleukin (IL)-1β, IL-6 and myeloperoxidase in BAL fluid were significantly inhibited by imatinib or nilotinib in mice of ALI during neutropenia recovery." (PMID 23787115, 2013). "Moving on an alteration of white cells, when we must deal with a neutropenia, it is suggested to choose an anti-TNF as first-line therapy: when this is not possible, not other drugs have specific evidence to be more adequate." (PMID 38979406, 2024). "Compared with naive brain, SAH induction in the absence of neutropenia significantly enhanced the tissue expression of all three inflammation markers (IL-1β: 477 ± 99%; TNFα: 3978 ± 318%; iNOS: 150 ± 17%)." (PMID 31186479, 2019).
peripheral nerve injury (52 papers, 2005 to 2025). Injury to a peripheral nerve. "IL-6 is predominantly induced as challenged by PGE2 and TNF-α in peripheral nerve injury, and is implicated in neuropathic pain via MAPK and STAT3 signaling." (PMID 38419042, 2024). "Notably, spinal ROS production, microglia activation, and production of proinflammatory cytokines, such as TNF-α or IL-1β, were ameliorated in Nox2-deficient mice after peripheral nerve injury." (PMID 35740059, 2022). "After peripheral nerve injury, microglial cells are activated by molecular mediators such as neuregulin-1, chemokine (C–C motif) ligand 2, and fractalkine; activated microglial cells in turn release IL-6, IL-1β, and TNF-α to cause painful symptoms." (PMID 36348269, 2022). "In case of peripheral nerve injury, the damaged neurons send excitatory signals to the spinal microglia via chemical substances, such as ATP and chemokines; these, in turn, cause microglial proliferation and upregulation of inflammatory cytokines, such as TNF-α, IL-1β, and IL-6, resulting in NP." (PMID 32636748, 2020). "It reduces mechanical and cold hyperalgesia by suppressing pro-inflammatory mediators such as TNF-α, nitric oxide, and interleukins, and by scavenging reactive oxygen species, which are key contributors to peripheral nerve injury." (PMID 41020842, 2025). "Studies in rodent models of diabetic peripheral nerve injury have indicated that blocking pro-inflammatory interleukin-6 (IL-6) and tumor necrosis factor-α (TNF-α) expressions attenuates neuroinflammatory response and pathological damage." (PMID 41264657, 2025). "Several studies revealed that, in response to peripheral nerve injury, Nox2-expressing macrophages are recruited to DRGs, thereby promoting ROS production and upregulation of TNF-α." (PMID 35740059, 2022). "TNF-α has been shown to be directly involved in pain responses in several animal models of peripheral nerve injury." (PMID 35008931, 2022). "For example, in greater detail: the levels of proinflammatory mediators like tumor necrosis factor-alpha (TNFα) or nerve growth factor are upregulated at the sites of peripheral nerve injury." (PMID 34295221, 2021). "TNF-α also improves the channel function in sensory neurons and leads to peripheral nerve injury, thereby inducing pain." (PMID 33777989, 2021). "SC, the most abundant peripheral glial cells, respond to peripheral nerve injury by the way of changing phenotype and releasing of inflammatory mediators (TNF-α, IL-6, and IL-1β), which leads to the exacerbation of NP." (PMID 34630095, 2021). "In the present research, we have found that peripheral nerve injury-induced microglia activation in the spinal cord dorsal horn can produce and release inflammatory mediators including TNF-α." (PMID 32393298, 2020). "Activation of miR-195 by peripheral nerve injury aggravates neuropathic pain via autophagy and this also leads to increases of IL-1β, and TNF-α." (PMID 32296644, 2020). "During peripheral nerve injury, activated glial cells release TNF-α and IL1-β, which affect the neurons and amplify the pain response." (PMID 28793053, 2017). "The pro-inflammatory cytokines, especially TNF-α and IL-1β, induced by peripheral nerve injury, are essential triggers for the activation of JNK in spinal astrocytes underlying the development of neuropathic pain." (PMID 25889689, 2015). "During Wallerian degeneration after peripheral nerve injury, pro-inflammatory cytokines, such as TNF-α, IL-1, and IL-6, are produced in the distal stump and/or recruited through circulation." (PMID 26629691, 2015). "Another issue regarding the use of TNF-α antagonists for peripheral nerve injuries or disorders is their value as a modulator of pain sensitivity." (PMID 23469058, 2013). "TNFα was shown to have a significant contribution in the development of pain sensitivity following peripheral nerve injury." (PMID 24067145, 2013).
peripheral nerve injury (continued). "The cytokine tumor necrosis factor α (TNFα) is now recognized as a pain modulator participating in both the peripheral and central processes leading to neuropathic pain following peripheral nerve injury." (PMID 22189061, 2011). "Thus, after peripheral nerve injury, increased TNF‐α/FFAs activate JNK‐1 and mTOR pathways, directly promoting IRS‐1 phosphorylation at inhibitory serine sites (Ser307/Ser612/Ser616)." (PMID 41414737, 2025). "Furthermore, the recovery from neuropathic pain following peripheral nerve injury depends on the downregulation of IL-1 β and TNF- α responses." (PMID 38673830, 2024). "Finally, we also address the importance of sNAMs for the production of pro-inflammatory cytokines, especially TNF and IL-1b, which have been described as upregulated in the sensory ganglia after peripheral nerve injury." (PMID 37254842, 2023). "Tumor necrosis factor-α (TNF-α) is a proinflammatory factor involved in peripheral nerve injury." (PMID 34159207, 2021). "In addition, we found that microglia in the S1 up-regulate the expression of proinflammatory cytokines, including TNF-α, after peripheral nerve injury, and depletion of microglial BDNF prevents the increase of TNF-α." (PMID 34292944, 2021). "It should also be noted that cytokine production is not wholly maladaptive as both interleukin-1β (IL-1β) and tumor necrosis factor-α (TNF-α) have been implicated in functional recovery after peripheral nerve injury." (PMID 33093824, 2020). "Besides, several inflammatory mediators are produced as a response to peripheral nerve injuries, such as TNF-α and IL-6." (PMID 32867013, 2020). "Therefore, we suggest that TNFα from microglia is a key molecule that initiates the production of PGI2 in endothelial cells after peripheral nerve injury." (PMID 28451639, 2017). "It is also known that peripheral nerve injury induces the expression of proinflammatory cytokines, such as TNF-α and IL-1β, in the DRG and that these cytokines may play a role in the development of pain hypersensitivity." (PMID 21951975, 2011). "TNF-α has several inflammation-mediating capabilities during peripheral nerve injury." (PMID 16287511, 2005). "A key factor in the initiation and maintenance of neuropathic pain, tumor necrosis factor α (TNF-α), is over-expressed in peripheral afferents, the spinal cord, and brain regions associated with pain processing, as well as in the ACC following peripheral nerve injury." (PMID 37895135, 2023). "Additionally, peripheral nerve injury also leads to the activation of peripheral (Schwann cells) and central (microglia and astrocyte) glial cells and begins to secrete proinflammatory cytokines, including TNFα, IL-1β, and PGE2." (PMID 35685245, 2022). "However, no significant changes in the expression of macrophage/glial cell activation markers and their derived pro-nociceptive cytokines (TNF and IL-1β) were detected after peripheral nerve injury in the DRGs and spinal cord from IL-27 null mice compared to WT mice." (PMID 32047492, 2019). "The expression of TNF-α, IL-6, and other pro-inflammatory factors in the DRG have been found to be increased after peripheral nerve injury." (PMID 35493326, 2022). "Peripheral nerve injury leads to activation of corresponding DRG macrophages and local spinal cord inflammation through activation of glial cells, recruiting and releasing TNF-α, IL-6, or monocyte chemoattractant protein-1 by immune cells." (PMID 34813418, 2022). "In more complex animal models of neuropathic pain such as peripheral nerve injury (PNI), TNFα is elevated both centrally and peripherally, and TNF antagonists can be effective in relieving pain." (PMID 34938263, 2021). "The cytokines IL6, TNF, IL10, IL2, and IL4 are all immunomodulatory factors, among which TNF and IL-6 have been confirmed to be involved in the pathological process of peripheral nerve injury." (PMID 33299447, 2020).
peripheral nerve injury (continued). "Activated glial cells release the proinflammatory cytokine TNF-α, which acts on TNF-R1 expressed by DRG neurons, enhancing their sensitivity to mechanical and thermal stimuli following peripheral nerve injury." (PMID 33505232, 2020). "Along with this immune cell infiltration, various proinflammatory cytokines and chemokines, including TNF-α, IL-1β, and MCP-1, are expressed in the DRG of injured nerves after peripheral nerve injury." (PMID 21951975, 2011). "In addition, activated microglia produce inflammatory mediators, such as interleukin (IL)-1β, IL-6, and tumor necrosis factor (TNF)-α, which are also produced in the spinal cord following peripheral nerve injury." (PMID 37122619, 2023). "Necroptosis triggered by TNF-α in the PV-INs of the ACC may be a key contributor to the E/I imbalance in the ACC and neuroimmune responses following peripheral nerve injury." (PMID 37895135, 2023). "Altogether, these results indicated that sNAMs are the main source of CX3CR1 signaling-dependent pro-inflammatory cytokines (e.g. IL-b and TNF) in the sensory ganglia after peripheral nerve injury, whereas IL-6 seems to be induced mainly in non-immune cells." (PMID 37254842, 2023). "Because IL-1, TNF-α, and TGF-β are increased during peripheral nerve injury in rats, it is thought that the higher NOX2 levels in the facial nerve in the injured (left) side compared with the uninjured (right) side might reflect induction of NOX2 expression by these inflammatory cytokines." (PMID 35203501, 2022). "Additionally, TNF-α is expressed in DRG neurons and is upregulated after peripheral nerve injury." (PMID 33727914, 2021). "Our results indicate that the PAF/PAFR system has an important role in production of TNFα and IL-1β in the DRG and tactile allodynia following peripheral nerve injury and suggest that blocking PAFRs may be a viable therapeutic strategy for treating neuropathic pain." (PMID 20454616, 2010).
cyst (51 papers, 2007 to 2026). A sac-like closed membranous structure that may be empty or contain fluid or amorphous material. "We demonstrate that IL-2+TNF-α+Th2+ triple-positive AgB-specific CD4+ T-cells and TNF-α+Th2+ double-positive AgB-specific CD4+ T-cells associate with cyst biological activity, being significantly increased in the active CE stages." (PMID 26575186, 2015). "An increase in TNF-α in renal tissues can also be caused by injury or infection or by cystic conditions as the cytokine was found to accumulate in cyst fluid from human ADPKD patients." (PMID 20587063, 2010). "TNF-α induces MIF expression, which in turn amplifies TNF-α expression in CLECs, forming a positive feedback loop that intensifies cyst progression." (PMID 41431718, 2026). "TNF-α level was elevated in human ADPKD cyst fluids and increased significantly with age in Cpk mice." (PMID 41431718, 2026). "As mentioned, several studies have documented the pivotal role of cytokines in cystogenesis and disease progression, as exemplified by the increased levels of IL-1β and TNF-α by ELISA, or osteopontin with mass spectrometry within the cyst." (PMID 39940890, 2025). "Tumor necrosis factor-α (TNF-α) is particularly important because it stimulates cyst growth in vivo, and it forms a positive feedback loop with NF-κB." (PMID 38540216, 2024). "When these same 3 bile acids were individually coincubated with 20 ng/mL TNF-α, cyst diameters decreased 3.5±0.6- (TCA), 4.8±0.6- (GCA), and 5.4±0.6-fold (GCDCA), respectively (p<0.05)." (PMID 38407207, 2024). "In relation to the priming induced by TNF-α treatment, neutrophils incubated in cell-free cyst fluid displayed a higher extent of priming compared to neutrophils incubated in cell-free ascites." (PMID 39759523, 2024). "Proinflammatory cytokines IL-1β, TNF-α, and IL-2 were identified in the cyst fluid of human APKD kidneys." (PMID 39768851, 2024). "The increase of tumor necrosis factor alpha (TNF-α) and subsequent signal transduction promote cyst growth in ADPKD mouse models." (PMID 39456148, 2024). "The results showed that EgCF treatment significantly downregulated the expression of pro-inflammatory cytokines IL-6 and TNF-α in macrophages, similar to the cyst fluid of E. multilocularis." (PMID 37689671, 2023). "CE is associated with polyfunctional T-cell subsets (as IL-2+TNF-α+Th2+ triple-positive and TNF-α+Th2+ double-positive T-cells) related to cyst biological activity." (PMID 36136825, 2022). "It is challenging to determine if the increase in tissue cysts in the brains of these mice is a result of TNF-α and iNOS restricting tissue cyst development, or if more parasites make it to the brain prior to tissue cyst formation." (PMID 33344268, 2020). "Both egr depletion in testis smooth muscles and JNK signaling inactivation in cyst cells suppress the abnormalities, indicating that too much TNF induced by prolonged protein starvation disrupts the germline recovery via JNK signaling in cyst cells." (PMID 32669615, 2020). "In parallel, exposure to TNF-α to 3D Caco-2 cyst also attenuated the TJs integrity via dysregulating ZO-1 and OCCLUDIN on both mRNA and protein levels, and inducing deformed sinuous TJ belts at bicellular contacts." (PMID 30765731, 2019). "We demonstrate, for the first time to our knowledge, that polyfunctional T-cell subsets as IL-2+TNF-α+Th2+ triple-positive and TNF-α+Th2+ double-positive specific T-cells associate with cyst biological activity." (PMID 26575186, 2015). "In conclusion, we demonstrated, for the first time, that polyfunctional T-cells subsets as IL-2+TNF-α+Th2+ triple-positive and TNF-α+Th2+ double-positive specific T-cells associate with biological cyst activity." (PMID 26575186, 2015). "Tumor necrosis factor alpha (TNFα) is present in cyst fluid and promotes cyst growth in autosomal dominant polycystic kidney disease (ADPKD)." (PMID 26110849, 2015).